SRF (serum response factor)
Diseases named in the same sentence as SRF in open-access papers (continued):
Sharing a sentence is not in itself a finding about the gene and the disease.
heart failure (continued). "In studies in which SRF expression was ablated to various degrees and in a stage-specific manner, mutant mice presented with disrupted cardiomyocyte architecture, mitochondrial dysfunction, and abnormal heart size and were ultimately destined for cardiomyopathy that led to heart failure." (PMID 35681202, 2022). "Specifically, the relationship between SRF and the splicing event in human heart failure has not been adequately studied." (PMID 40869995, 2025). "Here, we identify a role for IR/IGF1R-mediated signaling in regulating a serum response factor (SRF)-mediated transcriptional program necessary for sarcomeric integrity in the adult heart, which if absent results in rapid development of heart failure." (PMID 36125265, 2022). "This suggests that changes in SRF activity are a consequence of changes in CELF-mediated regulation rather than a secondary result of compensatory pathways in heart failure." (PMID 23437181, 2013).
melanoma (17 papers, 2015 to 2025). A malignant, usually aggressive tumor composed of atypical, neoplastic melanocytes. "Collectively, these observations support a model that ectopic expression of WT-Bmal1 or dHLH-Bmal1 sequesters Myh9, modulates SRF activity, and promotes an immune resistant mesenchymal melanoma cell state associated with increased AP-1 enhancer activity." (PMID 38245503, 2024). "To further investigate the context for SRF essentiality in melanoma, we extracted all TFs that were directly linked to the skin tissue, because TFs are most likely to play a central role in controlling tissue‐specific gene expression." (PMID 33073517, 2020). "We further used CEN‐tools to discover and experimentally validate an association between the skin‐specific gene SOX10 and the SRF TF downstream of MAPK signalling in malignant melanoma." (PMID 33073517, 2020). "RAC1 P29S confers resistance to BRAF inhibitors through the SRF/MRTF signaling pathway, indicating that targeted SRF/MRTF therapy may overcome BRAF inhibitor resistance in melanoma patients with RAC1P29S mutations." (PMID 34804979, 2021). "SRF/MRTF inhibitors could present an attractive approach to tackling BRAF inhibitor resistance in melanoma caused by RAC1P29S compared with the use of RAC inhibitors, which have to date proved difficult to progress into the clinic." (PMID 31257073, 2019). "However, SRF/MRTF inhibitors mechanism of action is unknown as they have been shown to bind Pirin a transcription factor implicated in melanoma cells senescence, migration and progression." (PMID 34827551, 2021). "A promising example is the combinatory treatment of malignant melanoma with B-RAF inhibitors and SRF/MTRF inhibitors in a mouse model of malignant melanoma." (PMID 35454871, 2022). "SRF is also regulated by Rho GTPases and the Rho/SRF signaling has also been studied in terms of mechanisms including melanoma metastasis and fibrotic pathological pathways." (PMID 36232837, 2022). "Serum response factor (SRF), a transcription factor, has been implicated in resistance to targeted therapies as well as driving metastasis in melanoma." (PMID 34831420, 2021). "In melanoma, the transcription factor complex SRF/MRTF is a key RAC1 effector, which has generated a therapeutic resistance by inducing a mesenchymal-like state." (PMID 34804979, 2021). "RAC1 function is also known to be essential in KRAS induced tumor formation, and in KRAS oncogene addiction, so the potential exists for SRF/MRTF inhibition to be explored in a far greater range of tumors than just RAC1P29S melanoma." (PMID 31257073, 2019). "Our findings suggest that the critical RAC1 effector in melanoma is the transcription factor complex SRF/MRTF, which initiates a switch to a mesenchymal-like state characterized by therapy resistance." (PMID 31257073, 2019). "Two key publications further support the importance of Rho/MKL/SRF signaling in melanoma metastasis." (PMID 27600078, 2016). "More recently, Treisman and colleagues showed that MKL and SRF were critical for metastasis of BF16F2 melanoma cells." (PMID 27600078, 2016). "Altogether, however, biological insights from the sequencing and proteomic data are corroborated by functional luciferase reporter assays and tumorigenesis studies, supporting the connections between Bmal1, Myh9, MRTF/SRF, AP-1, melanoma cell states and immune evasion." (PMID 38245503, 2024). "The findings reported here suggest that SRF/MRTF inhibitors, in combination with BRAF inhibitors, could have utility in the treatment of BRAF mutant melanoma with an additional RAC1P29S mutation." (PMID 31257073, 2019). "Therapeutic targeting of SRF/MRTF may have potential to reverse BRAF inhibitor resistance in melanoma patients bearing the oncogenic RAC1P29Smutation." (PMID 31257073, 2019).
melanoma (continued). "Although RAC1 inhibitor drugs are not currently available in clinical practice, SRF/MRTF inhibitors in combination with BRAF inhibitors have recently been shown to be effective in the treatment of BRAF mutant melanoma cells with a co-occurring RAC1 P29S mutation." (PMID 36901733, 2023). "In previous studies, SRF has been shown to be activated by RAC1 P29S, initiating transcriptional programs that promote malignant progression of melanoma." (PMID 40959096, 2025). "Mechanistically, RAC1P29S has been shown to activate the PAK and AKT pathways and to drive a mesenchymal phenotypic switch via the SRF/MRTF transcriptional axis and promote melanoma progression and therapeutic resistance." (PMID 41034404, 2025). "Accordingly, it was recently described that active Rac1 modulates SRF/MRTF, which initiates a switch to a mesenchymal-like state characterized by therapy resistance in melanoma." (PMID 39513883, 2024). "This way, MRTF depletion or use of SRF/MRTF inhibitors (CCG-1423 and CCG-203971) in melanoma cells abolished melanocytic to mesenchymal transition and PLX4720 co-treatment with CCG-257081 overcame tumour growth in mice." (PMID 34827551, 2021). "Taken together, these data suggest that RAC1P29S activates SRF/MRTF via WAVE and ARP2/3, and also activates AKT, to suppress apoptosis and promote survival of melanocytes and melanoma cells." (PMID 31257073, 2019). "Here, we study the role of RAC1P29S in melanoma development and reveal that RAC1P29S activates PAK, AKT, and a gene expression program initiated by the SRF/MRTF transcriptional pathway, which results in a melanocytic to mesenchymal phenotypic switch." (PMID 31257073, 2019). "In situ hybridization demonstrated increased mRNA expression of two canonical SRF/MRTF targets in tumor cells, substantiating the finding of increased SRF/MRTF signaling in the RAC1P29S melanoma." (PMID 31257073, 2019). "More importantly, the associations explored in detail in this study such as the essentiality of SRF in skin and dependence of NRAS‐mutant melanoma on IGF1R and FURIN hold true in the integrated data set and with even higher confidence suggesting that these are indeed robust associations." (PMID 33073517, 2020). "Activation of MRTF-A/SRF pathway plays a critical role in the migration but not in the proliferation of B16 melanoma cells." (PMID 26295164, 2015). "The S-isomer of CCG-1423 rather than the R-isomer exhibited modestly but significantly higher inhibitory effects on the cellular events triggered by MRTF-A activation including serum response factor-mediated gene expression and cell migration of fibroblasts and B16F10 melanoma cells." (PMID 26295164, 2015). "In summary, endogenous expression of RAC1P29S in BRAF-driven melanoma produces a less melanocytic and more mesenchymal differentiation state and generates resistance to the BRAF inhibitor PLX4720, which can be substantially reversed by co-treatment with an SRF/MRTF inhibitor." (PMID 31257073, 2019).
hepatocellular carcinoma (16 papers, 2013 to 2026). A malignant tumor that arises from hepatocytes. "MRTF and SRF transcriptional activity play an important role in hepatocellular carcinoma (HCC) growth, which represents the second leading cause of cancer-related mortality in humans worldwide." (PMID 36577757, 2022). "SRF is highly expressed in gastrointestinal cancers, such as hepatocellular carcinoma, CRC and esophageal cancer." (PMID 35198444, 2022). "FA-SRF-BSANPs can promote the intracellular uptake of hepatoma cells (SMMC-7721) with the strongest inhibitory effect compared with SRF-BSANPs and sorafenib solution." (PMID 30744448, 2019). "We find a matching association of RASSF1A and SRF in hepatocellular carcinoma (TCGA; P < 0.0001), again with significant linear correlation of RASSF1/SRF transcripts (R = 0.29) and further correlations with bladder and colorectal cancer (Fig EV6)." (PMID 31414556, 2019). "Myocardin-related transcription factor A (MRTF-A) is a coactivator of serum response factor (SRF), which regulates the expression of genes involved in cell proliferation, migration, and differentiation and has been implicated in hepatocellular carcinoma (HCC) progression." (PMID 39262570, 2024). "As senescence induction is an emerging strategy for the treatment of HCC, it is possible that intervening in the MKL1/2—SRF-MYOF signaling pathway may contribute to the treatment of hepatocellular cancer." (PMID 31828126, 2019). "Both MLK 1/2 and SRF are oncogenic drivers for hepatocellular cancer." (PMID 31828126, 2019). "SRF is expressed in mature soft tissues such as lung, liver and prostate and has been noted to be dysregulated in a number of malignant tissues such as prostate, breast, gastric and liver carcinoma." (PMID 28249598, 2017). "MRTF-A and SRF play an important role for tumor growth and senescence of hepatocellular carcinoma (HCC)." (PMID 41317652, 2026). "In the hepatocellular carcinoma (HCC) cell line, the silencing of the transcriptional coactivator of the serum response factor (SRF), Megakaryoblastic Leukemia 1/2 (MKL1/2), induced a reduction of myoferlin gene expression." (PMID 31443490, 2019). "For example, SRF expression in hepatocellular carcinoma (HCC) cells that can undergo EMT may play an enhanced role in tumor progression." (PMID 25303231, 2014). "For example, miRNA-122 inhibits the tumorigenic properties of hepatocellular carcinoma cells by repressing ADAM10 (a disintegrin and metalloprotease family 10), SRF (serum response factor), and Igf1R (insulin-like growth factor 1 receptor), which promote tumorigenesis." (PMID 28159933, 2017). "Myocardin-related transcription factor A (MRTF-A) is a coactivator of serum response factor (SRF), which regulates the expression of genes involved in cell proliferation, migration, and differentiation and plays an important role in hepatocellular carcinoma (HCC) growth." (PMID 39262570, 2024).
prostate carcinoma (16 papers, 2010 to 2025). A carcinoma that arises from epithelial cells of the prostate gland. "Considering that SRF expression has been associated with prostate cancer progression and resistance to enzalutamide in patients, we propose to target SRF as a therapeutic strategy to treat CRPC." (PMID 33260953, 2020). "Kaplan–Meier analysis in this cohort of patients also validated our previous study, showing that SRF expression is associated with survival from diagnosis with prostate cancer and with time to developing resistance to androgen deprivation therapy." (PMID 33260953, 2020). "Our study has identified one central factor, the serum response factor (SRF), which controls many genes associated with prostate cancer development." (PMID 33260953, 2020). "Here, we confirmed our previous studies on SRF association with survival from diagnosis with prostate cancer, and CRPC in an independent cohort of patients who died with CRPC." (PMID 33260953, 2020). "SRF has been associated with prostate cancer development and progression, and our group have previously studied its role in the development of castration resistance." (PMID 28249598, 2017). "SRF up-regulation was shown to be an early event during prostate cancer progression, being associated with biochemical recurrence, and also a biomarker of progression, with higher levels of SRF associated with castrate resistance, decreased survival from diagnosis and response to docetaxel." (PMID 33260953, 2020). "Our research group and others have previously reported that SRF nuclear positivity is associated with higher Gleason score in primary prostate cancer tissues and castrate-resistant TURPs suggesting that SRF may play a role in prostate cancer progression." (PMID 28249598, 2017). "Our group and others identified the serum response factor (SRF), a transcription factor involved in cytoskeleton organisation and cellular proliferation, as an important factor in prostate cancer progression in vitro and in vivo." (PMID 33260953, 2020). "Further studies are needed to investigate the role of α-tubulin acetylation, androgens levels and AR expression, as a link between SRF inhibition and AR sub-cellular localisation in prostate cancer." (PMID 33260953, 2020). "We also confirmed the relevance of SRF to patients by looking at its abundance in prostate cancer tissues from patients." (PMID 33260953, 2020). "In this study, we propose to inhibit SRF, a co-regulator of AR in prostate cancer, as a possible way to overcome resistance to enzalutamide." (PMID 33260953, 2020). "The relevance of SRF protein expression in prostate cancer patients was demonstrated in several published studies, highlighting the clinical relevance of this protein and the possibility of using it as a therapeutic target and a disease biomarker." (PMID 33260953, 2020). "The TAZ promoter region contains binding sites for E26 (ETS), forkhead box (FOXO) and serum response factor (SRF) transcription factors and has been previously reported bound by ETS transcription factor variants ETV1, 4, and 5 in prostate cancer." (PMID 32326412, 2020). "IHC analysis to quantify nuclear expression of the identified TF SRF correlates with both survival from date of bone metastasis (p = 0.003), survival from androgen independence (p = 0.00002), and overall survival from prostate cancer (p = 0.0044)." (PMID 28249598, 2017). "We recently identified a compound, CCG-1423, which blocks Rho/MKL/SRF-mediated transcription and inhibits PC-3 prostate cancer cell invasion." (PMID 27600078, 2016). "We have identified several transcriptional programs that are modulated in PC-3 human prostate cancer cells by our Rho/MKL/SRF transcription inhibitor CCG-1423." (PMID 27600078, 2016).
prostate carcinoma (continued). "The expression of the Arg388 protein led to increased activity of the extracellular signal-related kinase (ERK) pathway, serum response factor, and transcription of multiple genes, which are correlated with aggressive clinical behavior in prostate cancer." (PMID 27640814, 2016). "Some of the regulators affected by this treatment however could be implicated in anti-tumorigenic activities (i.e., IL-6), yet modulation identified in other regulators are potentially implicated in prostate cancer tumorigenesis, such as BHLHE40, and SRF." (PMID 38078010, 2023). "Importantly, in prostate cancer patients, SRF expression positively correlates with TAZ and the YAP/TAZ target genes CYR61 and CTGF." (PMID 37385752, 2023). "Our findings dissect the cellular roles of YAP, TAZ, and SRF in prostate cancer cells." (PMID 37385752, 2023). "Due to the potential use of SRF as a therapeutic target in advanced prostate cancer and its relationship with AR, in this study, we tested the combination treatment of enzalutamide and CCG1423 in vitro and in LuCaP 35CR, a patient-derived xenograft (PDX) model of enzalutamide resistance." (PMID 33260953, 2020). "Our results suggest that SRF could be one such marker, and may also represent a therapeutic target in the treatment of men afflicted with advanced prostate cancer." (PMID 28249598, 2017). "Coupled together these findings further suggest that SRF may play a role in progression of prostate cancer, and maybe an amenable therapeutic target for manipulation at various disease stages." (PMID 28249598, 2017). "In order to investigate the functional role of SRF we undertook SRF siRNA knockdown experiments and demonstrated significant reversal in resistance to docetaxel in our PC-3 model of docetaxel resistant prostate cancer." (PMID 28249598, 2017). "This study gave us the opportunity to expand our understanding of SRF’s role in docetaxel resistance, in the context of AR negative and docetaxel resistant PC-3 cells, and clinical tissues from castrate and docetaxel resistant prostate cancer." (PMID 28249598, 2017). "Our results suggest that SRF could aid in treatment stratification of prostate cancer, and may also represent a therapeutic target in the treatment of men afflicted with advanced prostate cancer." (PMID 28249598, 2017). "Moreover, a clinically relevant androgen-dependent gene signature under SRF regulation was identified which could distinguish between indolent and aggressive prostate cancer." (PMID 33260953, 2020). "SRF has also recently been associated with androgen receptor (AR) hypersensitivity; where a negative feedback loop exists between SRF expression and AR transcriptional activity in the setting of castrate-resistant prostate cancer." (PMID 28249598, 2017). "18βGA repressed androgenic and survival responses in prostate cancer cells by inducing tumor-suppressive miR-488 and transcriptional downregulation of AR via modulating E2F transcription factor 3 (E2F3)α and serum response factor (SRF) activity on the androgen receptor promoter." (PMID 36903944, 2023). "A dual requirement of SRF and myocardin for regulation of PTRF, but not for regulation of CAV1, suggests a mechanism for uncoupling of PTRF synthesis from CAV1 synthesis, such as seen in prostate cancer cells." (PMID 26244347, 2015).